NEU1 (neuraminidase 1)
Diseases named in the same sentence as NEU1 in open-access papers (continued):
Sharing a sentence is not in itself a finding about the gene and the disease.
cancer (continued). "In cancer cells, the downregulation of the lysosomal sialidase NEU1 induces the accumulation at the lysosomal membranes of over-syalilated LAMP1, that in turn promotes lysosomal exocytosis of hydrolases and exosomes." (PMID 32276321, 2020). "We have conducted an integrated analysis of genomic, epigenomic, and transcriptomic data to estimate how the key SA genes, namely CMAS, ST3GAL1, ST3GAL5, and NEU1, are regulated across different cancer types." (PMID 32296639, 2020). "In a summary of TMA analysis results, NEU1 expression was significantly lower in cancer tissue than in matched normal tissue for 40 of the 44 pairs." (PMID 32164705, 2020). "In contrast to sialic acid expression, NEU1 expression was higher for HCV29 than for the four cancer cell lines." (PMID 32164705, 2020). "Our data showed that NEU1 inhibited cancer cell proliferation, induced apoptosis, and suppressed tumor formation both in vitro and in vivo, by disrupting interaction of FN and integrin β1 and inhibiting the Akt signaling pathway." (PMID 32164705, 2020). "Recently, it has been documented that NEU1 has a potential role in the regulation of cell proliferation, migration, invasion and cancer metastasis 25-27." (PMID 33123278, 2020). "Altogether, these data indicate that Neu-1 plays a key role in the development and the amplification of several cancers and can constitute a new target to slow down cancer progression." (PMID 32351895, 2020). "Initially, we compared the status of Neu1/Neu2/Neu3/Neu4 in cancer and normal tissue specimens by immunohistochemistry." (PMID 29434218, 2018). "The SNP rs12193504 is located close to the NEU1 gene, which has been studied extensively in cancer and suggested to have a profound effect in human cancers." (PMID 29547645, 2018). "This review summarizes the recent studies that identify the tumor-specific role of the structures within our model, and emphasizes the importance of Neu1 as a new target in cancer treatment." (PMID 27029067, 2016). "Pathway analysis revealed that spliceosomal function in addition to other cancer-related pathways were altered following changes in NEU1 expression." (PMID 27602751, 2016). "Recent evidence indicates that Neu1 plays a much more profound role in human cancers than previously expected." (PMID 27029067, 2016). "While NEU1 has been shown to be upregulated in cancer cells in previous reports, there existed controversy regarding the effect of NEU1 in different tumors." (PMID 27602751, 2016). "In summary, the reports in this review implicate Neu1 as a novel therapeutic target in cancer therapy, and as a promising intervention in multistage tumor development." (PMID 27029067, 2016). "We propose here a graphical abstract illustrating that the Snail-MMP-9 signaling axis maintains several important cancer growth factor receptor signaling platforms in promoting Neu1-MMP-9 crosstalk in complex with these receptors." (PMID 26932374, 2014). "Recent studies also indicate that NEU1 product Neu1 salidase is important in regulation of integrin β4-mediated signaling, leading to suppression of cancer metastasis." (PMID 25184537, 2014). "Furthermore, we have shown that treatments targeting Neu-1 were very effective at disrupting cancer cell metastasis in preclinical animals." (PMID 40227834, 2025). "Moreover, Neu-1, a regulator of these receptors, is a novel targeted approach for cancer therapeutics." (PMID 36831374, 2023). "These pathways are also involved in MMP-9/Neu-1 cross-talk, highlighting that transactivation of the IR is likely mediated by Neu-1 to promote signaling pathways involved in tumorigenesis, and its downregulation will likely lead to a decrease in cancer viability." (PMID 36831374, 2023). "Experimental studies have shown that OP and NMBR inhibitor BIM-23127 inhibits independent autophosphorylation of IRβ and IRS-1 in HTC-IR cells, blocking Neu-1-mediated transactivation of the IR, which may be used as a therapeutic target for cancer." (PMID 36831374, 2023).
cancer (continued). "Evidence suggests that the upregulation of NEU1 in cancers may increase the utilization of sialic acid, thus contributing to the maintenance of cell sialylation." (PMID 37372117, 2023). "After comparing the status of Neu1/Neu2/Neu3/Neu4 in cancer and then in normal tissue specimens, it was concluded that the loss of Neu2 may aid in greater sialylation status in pancreatic cancer manifestation." (PMID 36547200, 2022). "In summary, the reports in this review suggest that NEU-1 could be a novel therapeutic target in cancer therapy." (PMID 36230790, 2022). "The aim of this review is to describe the role of NEU-1 in several metabolic diseases and cancers and to show that this protein could be considered in some cases as a link between these two physiopathological contexts." (PMID 36230790, 2022). "Moreover, a high NEU-1 expression is correlated with advanced cancer stages or grades and a notably shorter overall survival for all HCC patients." (PMID 36230790, 2022). "Thus, since the EDP effects are linked to the ERC complex and that the EDPs play a role in the invasive and metastatic capacities of tumors, we will describe, in this part, the role of NEU-1 in the onset and the progression of cancers." (PMID 36230790, 2022). "As NEU-1 is involved in metabolic diseases and several cancers, this protein could be considered in some cases as a link between these two physiopathological contexts." (PMID 36230790, 2022). "Published data investigating the role of NEU1 in cancer are somewhat contradictory." (PMID 36077781, 2022). "Interestingly, the NEU-1 activity level in the same cancer tissues seemed to be inversely correlated with the extent of the invasion and a poor differentiation." (PMID 36230790, 2022). "In other cancer models, NEU1 has been found to be a positive regulator of cell migration." (PMID 35281276, 2022). "Main functions, in particular of NEU1, are described for cancer progression." (PMID 33572654, 2021). "It has been reported that NEU1 could regulate epithelial mesenchymal transformation which is thought to be involved in the invasion and metastasis of cancer, leading to poor prognosis." (PMID 34513919, 2021). "A recent report has suggested that neuraminidase-1 (Neu1) could be a novel therapeutic target for cancer treatment and is expected to become an intervention for multi-stage cancer development." (PMID 34513919, 2021). "Furthermore, we observed that the NEU1 expression was significantly related to the T stage, pathologic stages, and grades, and a trend toward increased NEU1 expression with advanced cancer stages or grades." (PMID 34513919, 2021). "Indeed, the desialylation activity of Neu1 has been shown to regulate cancer growth, and its selective inhibition has demonstrated significant therapeutic results in murine models of cancer." (PMID 27029067, 2016). "Collectively, we propose here that Neu1 is a novel alternate candidate target using OP therapy in restraining the growth, metastases, tumor neovascularization as well as macrophage-mediated tumorigenesis of human cancers." (PMID 27608845, 2016). "Since the co-expression of EGFR and MMP-9 has prognostic value in cancer, and Neu1 and MMP-9 cross-talk regulates EGFRs in pancreatic cancer cells, we investigated the molecular targeting potential of the Neu1–MMP9 crosstalk platform in human ovarian cancer cell lines in vitro." (PMID 26932374, 2014). "Therefore, targeting aberrant NEU1 expression may represent a promising clinical strategy for managing metabolic adaptability in the heart, potentially improving clinical outcomes for cancer patients undergoing chemotherapy." (PMID 40411250, 2025). "NEU1 is fundamentally involved in the coordination of various cellular metabolic behaviors and signaling in vivo, thereby impacting the onset and development of related diseases, such as cardiovascular diseases, neurological disorders, respiratory diseases, hematological diseases, and cancer." (PMID 39194692, 2024).
cancer (continued). "Moreover, the results suggest that strong CB1 signaling may result in biased agonism where consistent signaling of the CB1 receptor may upregulate GPCRs, including Neu-1, which have a malignant effect on cancer." (PMID 38534324, 2024). "Here, we used synthetic CB1 cannabinoids and found them to upregulate cancer cell viability, EMT markers, and migration involving this Neu-1 signaling paradigm." (PMID 39851499, 2025). "This work demonstrates that increased NEU-1 expression is essential in EGFR signaling, which promotes cancer progression and metastasis." (PMID 39194692, 2024). "Even if several membrane proteins can be targeted by this approach, three examples will be described in this section: Neu-1, DDR1, and GPCRs which are involved in several cancer processes." (PMID 32351895, 2020). "Cumulatively, the findings presented here indicate that targeting Neu-1 may inhibit the process of EMT and disrupt the metastatic potential of cancer cells." (PMID 40227834, 2025). "Lysosomal neuraminidase (NEU1) enhances lysosomal exocytosis and lysosomal hydrolase activity, remodeling the extracellular matrix within the tumor and invading the neighboring tissue thus promoting cancer metastasis." (PMID 40066097, 2025). "Overall, a consistent role of NEU1 in different tumors has not been established, with either too high or too low expression of NEU1 being a driver of divergent effects on different cancers." (PMID 39194692, 2024). "Finally, they demonstrated that an increased NEU-1 expression was essential in MMP-9-EGFR signaling and it promotes cancer progression and metastasis." (PMID 36230790, 2022). "Furthermore, oseltamivir phosphate (OP) has been reported to inhibit mammalian Neu-1 in complex with MMP-9 and GPCR tethered to several RTKs, many of which are overexpressed on cancer cells." (PMID 35326525, 2022). "The evaluation of human NEU-1 expression by a quantitative RT-PCR in colon cancer showed that there is a lower expression of it in cancer tissues than there is in the adjacent non-cancerous mucosa." (PMID 36230790, 2022). "This approach can be extended to inhibit other TM protein dimerization such as neuraminidase-1 (Neu-1, the catalytic subunit of elastin receptor complex), DDR1 (Discoidin Domain Receptor 1, a RTK activated by type I collagen) and GPCRs which are involved in cancer processes." (PMID 32351895, 2020). "Most significantly, the treatment of patients with specific inhibitors of Neu-1 soon after primary cancer surgery may improve our ability to cure early-stage cancer by inhibiting the EMT process and disrupting the ability of any residual cancer cell population to metastasize." (PMID 40227834, 2025). "There is no debate that the increased expression of Neu-1 and MMP-9 has an impact on cancer progression through the modulation of inflammation, tumorigenesis, and insulin receptor signaling." (PMID 38534324, 2024).
tumor (35 papers, 2009 to 2026). "Mechanistically, we show that the transforming pathway is increased lysosomal exocytosis downstream of reduced neuraminidase 1, exemplified by the redistribution of the lysosomal associated membrane protein 1 at the plasma membrane of tumor and stromal cells." (PMID 36127469, 2022). "These combined observations were not seen in normal muscle tissue of these mice, emphasizing that the connective tissue deposition observed in the NPE RMS tumors was caused by the combination of reduced activity of Neu1 within tumor cells and stroma." (PMID 36127469, 2022). "It is also demonstrated that the expression level of NEU1 in tumor tissue is a prognostic marker for HCC, associated with the survival time and specific clinicopathological features of HCC." (PMID 27602751, 2016). "Higher expression of NEU1 is associated with increased proliferation, migration, and lower levels of B cells, T-cells, and natural killer (NK) cells, regulating several tumor-related proteins and pathways, such as lysosome, spliceosome, and mTOR signaling pathways." (PMID 37601653, 2023). "Further RRM2, GMPS, BCAT1, PYCR2, and NEU1 are identified in tumor tissue as actionable candidates for prevention." (PMID 40290517, 2025). "In ovarian, pancreatic, hepatocellular and melanoma cancers, inhibition of NEU1 is a potential target for tumor therapy." (PMID 40221400, 2025). "KEGG analysis demonstrated that circadian rhythm pathway was significantly enriched on both 3 d and 7 d, genes related to disease/tumor, including Tns4 and Neu1 (upregulated), as well as Npas2 and Cry1 (downregulated), exhibited obvious changes." (PMID 39727670, 2025). "Experimentally, it was confirmed that NEU1 overexpression inhibits tumor formation in vivo and in vitro by inhibiting the proliferative and metastasizing tendencies of tumor cells." (PMID 39194692, 2024). "Other enzymes in the same signature belonging to the lysosomal pathway of ganglioside catabolism, such as Hexosaminidase Subunit Beta (HEXB) and Neuraminidase 1 (NEU1), were also overexpressed in tumor samples of both LIHC and LIRI-JP." (PMID 38927057, 2024). "NEU1 is upregulated in HCC tumor tissues, which correlates with advanced stage, grade, and worse survival of HCC patients." (PMID 37601653, 2023). "NEU1 significantly induced apoptosis and inhibited tumor formation by interfering with Akt signaling pathway." (PMID 38201173, 2023). "An experimental study demonstrated that NEU1 siRNA can significantly suppress proliferation, apoptosis, and invasion of tumor cells by targeting lysosomal membrane proteins (CLN3 and CLN5)." (PMID 34513919, 2021). "The YTS-1/NEU1-injected mice showed significantly slower tumor growth, and a much smaller total tumor mass, in comparison to YTS-1/Ctrl-injected mice." (PMID 32164705, 2020). "Examination of Neu tumor cells revealed four clusters (Neu-1 to Neu-4) with well-defined characteristics to allow illustration of their hierarchical relationships." (PMID 32840210, 2020). "We therefore took an experimental approach to test this idea using the Neu tumor due to its best-defined hierarchical structure from LPs (Neu-1) to AvPs (Neu-2) to AvDs (Neu-3)." (PMID 32840210, 2020). "NEU1 expression, at both the mRNA and protein levels, were also higher in the portal vein tumor thrombus than tumor tissues." (PMID 27602751, 2016). "In the present work we evaluated the expression of NEU1 in two independent cohorts, demonstrating that NEU1 was significantly upregulated in tumor tissue." (PMID 27602751, 2016). "In contrast, Neu1 and Neu3 were weakly expressed and lacked consistent tumor association, underscoring Neu2 as the dominant infiltrating subset." (PMID 40959269, 2025). "Additionally, KDSR and NEU1 in this pathway was found to be significantly upregulated along the trajectory indicating potential targets for the development of anti‐tumour strategies." (PMID 36855810, 2023).
tumor (continued). "Interestingly, these ECM proteins, which ultimately promote tumor progression, are disrupted by Neu-1 signaling." (PMID 35326525, 2022). "They further demonstrated that the therapeutic effectiveness of oseltamivir phosphate targeting NEU1 could restrict the tumor’s capacity to metastasize." (PMID 36547200, 2022). "Thus, reduced Neu1 expression promotes pleomorphism and transforms the tumor stroma into a desmoplastic, fibrotic state." (PMID 36127469, 2022). "Moreover, in tumor tissues with overexpressed NEU1, less proliferation and more apoptosis were observed." (PMID 32164705, 2020). "The importance of NEU1 in tumor formation in vivo was performed using BALB/c-nu mice." (PMID 32164705, 2020). "Optical density score conferred higher Neu1, Neu3, and Neu4 positivity in the tumor tissues." (PMID 29434218, 2018). "We also assessed the protein expression of NEU1 in tumor-normal paired samples from 18 patients." (PMID 27602751, 2016). "In addition, we found that several miR-125b target genes were down regulated and two of these BBC3 (PUMA) and Neu1 are known tumor suppressors." (PMID 25184537, 2014). "It has been reported that NEU1 modifies the tumor microenvironment and alters the tumor microenvironment by shearing the salivary acid modification of LAMP1, thereby regulating tumor development and drug resistance." (PMID 40221400, 2025). "The expressions of NEU1 and CSTA were significantly increased in tumor tissues compared with those in the resection margins." (PMID 40141206, 2025). "NEU1 negatively regulates the extracellular actions of lysosomes by cleaving LAMP1, thereby affecting tumor invasiveness." (PMID 39194692, 2024). "Neu-1′s involvement in regulating glycosylated growth factors receptors such as IR, EGFR, and TrkA indicates it impacts a tumor’s characteristics, such as cell growth, proliferation, and differentiation." (PMID 36831374, 2023). "To assess the importance of NEU1 in tumor formation in vivo, we injected YTS-1/Ctrl or YTS-1/NEU1 cells into BALB/c-nu mice and assayed tumor growth." (PMID 32164705, 2020). "In tumor tissue, these pathways were significantly deregulated regarding gene and protein expression in two independent datasets, including actionable targets RRM2, GMPS, BCAT1, PYCR2, and NEU1." (PMID 40290517, 2025). "Further evidence of Neu-1′s involvement in IR signaling is that in-vitro and in-vivo studies have concluded that insulin affects tumor progression by acting on the IR and not solely by IGF-1R cross-talk." (PMID 36831374, 2023). "We also evaluated the expression of NEU1 in 19 normal-tumor-portal vein tumor thrombus (PVTT) paired samples, and found that the highest expression of NEU1 was observed in PVTT tissues, indicating the possible pro-metastatic role of NEU1." (PMID 27602751, 2016). "Thus, decreasing NEU1 protein levels may lead to activation of the AKT signaling pathway, which promotes tumor growth." (PMID 40221400, 2025). "Thus far, two of these target genes, BBC3 and NEU1, that are tumor suppressor genes but not yet studied in PDAC, appear to be functional targets of miR-125b since knockdown of miR125b caused their up regulation." (PMID 25184537, 2014). "It is important to emphasize that the effect of Neu1+/− is not in the generation of RMS, but rather in its pleomorphic transformation once the tumor is initiated; while ETV7 expression is promoting a high incidence of RMS formation in Ptch1+/− mice." (PMID 36127469, 2022). "Moreover, RNA-seq data from each of 40 advanced PDAC tumor specimens from the TCGA data base indicate a negative correlation between expression of miRNA-125b and five of six potential target genes (BAP1, BBC3, NEU1, BCL2, STARD13)." (PMID 25184537, 2014).